ENSG00000296382 (novel transcript)
Gene: Long non-coding RNA gene on chromosome 6 (27,791,697 to 27,796,268, forward strand). Ensembl gene ENSG00000296382.
Gene Ontology:
Molecular function: triplet codon-amino acid adaptor activity
Biological process: translation